PXMP2 (peroxisomal membrane protein 2)
Description:
Seems to be involved in pore-forming activity and may contribute to the unspecific permeability of the peroxisomal membrane.
Synonyms: PMP22; MPV17L3
Tractability: Antibody: UniProt predicts a signal peptide or a membrane-spanning region.
Gene: Protein-coding gene on chromosome 12 (132,687,587 to 132,705,098, forward strand). Ensembl gene ENSG00000176894.
Subcellular location: Peroxisome membrane
Pathways (Reactome):
Metabolism: Glyoxylate metabolism and glycine degradation
Protein localization: Class I peroxisomal membrane protein import
Gene Ontology:
Molecular function: protein binding
Cellular component: cytoplasm; membrane; peroxisomal membrane; protein-containing complex; cytosol
Genetic constraint (gnomAD): Loss-of-function variants: 12 observed, 17.49 expected, observed/expected ratio (o/e) 0.69, 90% interval 0.44 to 1.11. The upper end of that interval is the gene's LOEUF score, 1.11, which puts it in group 4 of 6, group 1 being the genes least tolerant of losing a copy. Missense variants: 237 observed, 209.36 expected, observed/expected ratio (o/e) 1.13, 90% interval 1.02 to 1.26. Synonymous variants: 91 observed, 87.86 expected, observed/expected ratio (o/e) 1.04, 90% interval 0.87 to 1.23.
Homologues: Orthologues: chimpanzee PXMP2 (99% identical), macaque PXMP2 (88% identical), guinea pig PXMP2 (80% identical), mouse Pxmp2 (76% identical), pig PXMP2 (76% identical), rat Pxmp2 (68% identical), rabbit PXMP2 (58% identical), tropical clawed frog pxmp2 (56% identical), zebrafish pxmp2 (53% identical), Drosophila melanogaster CG7970 (27% identical). Paralogues in human: MPV17 (29% identical), MPV17L2 (28% identical), MPV17L (21% identical).
Diseases named in the same sentence as PXMP2 in open-access papers:
PXMP2 is named in the same sentence as 5 diseases in open-access papers, as found by Europe PMC text mining. Sharing a sentence is not in itself a finding about the gene and the disease. The quoted sentences say what the papers report.
esophageal squamous cell carcinoma (1 paper, 2022). Esophageal squamous cell carcinoma (ESCC) is a type of esophageal carcinoma (EC) that can affect any part of the esophagus, but is usually located in the upper or middle third. "In a co-expression network analysis in esophageal squamous cell cancer, PXMP2 was found to be a hub gene possibly linked to lipid metabolism and potentially playing a role in esophageal squamous cell cancer progression." (PMID 36503519, 2022).
liver cancer (1 paper, 2022). An epithelial or non-epithelial malignant neoplasm that arises from the liver. "We found that expression of the Neanderthal PXMP2 allele was significantly higher than the modern human allele in liver cancer compared to unaffected livers." (PMID 36503519, 2022).
parasitic disease (1 paper, 2017). "Over both species, the strongest biomarkers for discrimination between viral and bacterial/parasitic disease were UBL1 (PXMP2), IFIT5, GAL3, NFX, VHSVIP4 (VIG4), DEXH (DDX58), unknown CA054694 MX1 RSAD, IFI44A, and HERC6." (PMID 28702195, 2017).
cancer (1 paper, 2017). A tumor composed of atypical neoplastic, often pleomorphic cells that invade other tissues. "From this limited gene list, carboxypeptidase E (CPE), fatty acid binding protein 7 (FABP7) and peroxisomal membrane protein 2 (PXMP2) were all previously found to be associated with human cancer." (PMID 29062039, 2017).
PXMP2 also shares sentences with these, for which no sentence is quoted: Fanconi anemia (1 paper).